NEAT1 (nuclear paraspeckle assembly transcript 1)
Diseases named in the same sentence as NEAT1 in open-access papers (continued):
Sharing a sentence is not in itself a finding about the gene and the disease.
tumor (continued). "However, the patients with high Enneking staging, large tumor size, and distant metastasis tended to have higher expression of NEAT1 in tumor tissues." (PMID 29654165, 2018). "BRCA1 is a tumor-suppressing gene that is located upstream of NEAT1." (PMID 28118609, 2017). "Therefore, NEAT1 probably affects the expression of certain tumor-related genes and further participates in the occurrence and evolvement of malignancies." (PMID 28118609, 2017). "Additionally, lncRNA growth-arrest-specific 5 (GAS5) plays tumor-suppressive roles in PC cells, whereas NEAT1, MALAT1, HOTTIP and HOTAIR exert oncogenic roles in PC cells." (PMID 29137412, 2017). "Therefore, a comprehensive meta-analysis of all eligible articles was performed to further evaluate the clinical feasibility of NEAT1 as a novel biomarker candidate as well as useful insights into the tumor clinicopathological features." (PMID 29026116, 2017). "We determined that NEAT1 is up-regulated in RCC tissue compared to corresponding non-tumor tissue." (PMID 28968960, 2017). "The expression of NEAT1 was lower in tumor tissues than in normal tissues." (PMID 29050268, 2017). "The data indicated that NEAT1 expression had a non-significant association with advanced tumor stage." (PMID 29050268, 2017). "NEAT1 can function to be oncogenic by sponging the tumor-suppressive microRNAs." (PMID 27926523, 2017). "The present results elucidate a potential mechanism underlying the tumor-oncogenic role of NEAT1 in NSCLC, and indicate that NEAT1 could be a useful marker and potential therapeutic target in NSCLC." (PMID 27351135, 2016). "In this study, we found that miR‐124‐3p is markedly decreased in OC patients, and its tumor suppressive roles might due to its regulation on NEAT1 expression." (PMID 27075229, 2016). "Moreover, patients with high NEAT1 expression had a poor differentiation and a shorter tumour-free survivaltime." (PMID 27788162, 2016). "In addition, GSCs treated with sh-NEAT1+pre-let-7e exhibited weaker migration abilities than controls in 3D Spheroid-based tumor migration assays." (PMID 27556696, 2016). "Moreover, GSCs treated with sh-NEAT1 exhibited weaker migration abilities than control cells in 3D Spheroid-based tumor migration assays." (PMID 27556696, 2016). "In the present study, we examined the expression levels of NEAT1 lncRNA in collected GAC and ANT samples and found that the expression levels of NEAT1 lncRNA were significantly enhanced in GACs and had an association with tumor stages." (PMID 26911892, 2016). "In human breast cancer, induction of NEAT1 in hypoxia could lead to accelerated tumor cell proliferation and reduced apoptosis, both of which would contribute to tumorigenesis." (PMID 26314847, 2015). "Furthermore, examining MDA-MB-231 xenografts for CA9 by immunostaining and NEAT1 by RNA-fluorescent in situ hybridization confirmed co-localization of NEAT1 with CA9 in regions distant from tumor blood vessels." (PMID 25417700, 2015). "In addition, NEAT1 was also demonstrated to drive oncogenic growth and tumor progression of prostate cancer by altering the epigenetic landscape of target gene promoters to favour transcription." (PMID 26314847, 2015). "The tumours were excised and weighed, and the NEAT1 shRNA group had significantly smaller tumours." (PMID 25415230, 2014). "Overexpression of NEAT1 could enhance the anti-tumor responses by intensifying ferroptosis in HCC." (PMID 38960924, 2024). "Moreover, NEAT1 interacts with miR-214 to regulate B7-H3 expression in multiple myeloma, leading to the polarization of macrophages to the M2 subtype, thereby inducing the formation of a tumor-immunosuppressive microenvironment." (PMID 39539540, 2024). "By modulating the functioning of genes linked to control of tumor cell proliferation, movement, spread, triggering of apoptosis, epithelial-to-mesenchymal transition (EMT), stem cell-like phenotype, resistance to chemo and radio-resistance, NEAT1 promotes the onset and growth of tumors." (PMID 38343745, 2024).
tumor (continued). "Although direct analysis of senescent and proliferative HCC cells may identify a different lncRNA for HCC senescence, our study identified NEAT1 as a representative senescent lncRNA in the common cellular senescence pathway during the malignant tumour progression." (PMID 37752791, 2023). "Furthermore, silencing of NEAT1 reduced the xenograft tumor growth." (PMID 37310654, 2023). "Thus, NEAT1 by suppressing miR-506 could regulate tumor cell growth, proliferation, progression, and cell–cell adhesion." (PMID 37310654, 2023). "Therefore, NEAT1 promoted tumor growth and tumorigenicity in vitro and in vivo." (PMID 37310654, 2023). "Depletion of NEAT1 markedly inhibited tumor growth in mice, while PGK1 could reverse this effect." (PMID 35123484, 2022). "In addition, the knockdown of NEAT1 also promoted T cell infiltration in a xenograft tumor model." (PMID 36011001, 2022). "Importantly, they could also demonstrate that downregulation of LRG1 via silencing of nuclear paraspeckle assembly transcript 1 (NEAT1) can prevent tumour cell migration and invasion." (PMID 34987199, 2022). "Finally, the effect of NEAT1 on the tumor volume of HCC was verified by animal experiments." (PMID 36185217, 2022). "However, other studies have shown that Lnc NEAT1 acts as a tumor suppressor." (PMID 35850692, 2022). "Thus, NEAT1 plays an important role in tumor resistance and tumorigenesis in CRC." (PMID 34938735, 2021). "Moreover, in vivo experiments indicated that silence of NEAT1 signally suppressed tumor growth." (PMID 34837887, 2021). "However, the correlation between NEAT1 and tumor angiogenesis has hardly been reported." (PMID 34552925, 2021). "Notably, NEAT1 knockdown delayed tumor growth in the model compared to the control group." (PMID 34263426, 2021). "However, whether the tumor suppressive function of NEAT1 stems from the long or the short transcript needs to be further investigated." (PMID 33142861, 2020). "Additionally, NEAT1 knockdown weakened tumor growth in vivo." (PMID 32336952, 2020). "In the current study, we demonstrated that NEAT1 sponges miR-361 and suppresses miR-361 expression, thereby activating miR-361-regulated networks involved in invasion, sphere formation and chemoresistance in aggressive EC cells and remodeling the surrounding tumor microenvironment." (PMID 31287002, 2019). "Therefore, the role of NEAT1 in tumor cells may be cell-type dependent, although this possibility needs to be further studied." (PMID 30185232, 2018). "Therefore, we hypothesized that NEAT1 facilitated tumor proliferation and metastasis in a DDX5-mediated manner." (PMID 30185232, 2018). "Although a number of genes are differentially expressed in tumours formed in Neat1 KO mice compared to the tumours formed in the wild-type mice, they might be secondarily affected and primary target molecules regulated by Neat1/paraspeckles remain to be investigated." (PMID 30355755, 2018). "Moreover, we found that NEAT1 expression was positively correlated with tumor size." (PMID 29764424, 2018). "Moreover, the tumor suppressor miR-34c was negatively regulated and inhibited by NEAT1 in OS." (PMID 29654165, 2018). "The ratio of the two isoforms of NEAT1 may determine the trends for tumor development." (PMID 28118609, 2017). "Thus, it is conceivable that let-7e, in contrast to NEAT1, functions as a tumor suppressor in GSCs." (PMID 27556696, 2016). "In the present study, we demonstrated that NEAT1_v1 could improve tumor cells growth and invasion, while NEAT1_v2 had reverse function in proliferation, which was somewhat in corresponding with the prognostic potential of whole blood NEAT1 expression." (PMID 26552600, 2015).
tumor (continued). "H19, NEAT1, and MALAT1 showed significantly altered expression in tumor tissue, as well as non-tumor tissue before and after nCRT." (PMID 41751809, 2026). "This study aimed to compare the expression of exosomal HOTAIR, NEAT1, MALAT1, AFAP1-AS1, ANRIL, and HULC lncRNAs in primary tumor tissue and blood of patients with sporadic TNBC to evaluate their potential as biomarkers." (PMID 42196289, 2026). "NEAT1 also modulates the immune landscape in the TME by modulating inflammatory mediators and promoting immunosuppression, which is conducive to tumour progression." (PMID 40896358, 2025). "Through its interaction with YB1, FGF12 enhances the expression and stability of oncogenic lncRNAs, including NEAT1 and MALAT1, thereby strengthening adaptive transcriptional programs that support tumor persistence." (PMID 41294881, 2025). "Furthermore, gma-miR159 from soybean inhibits TCF7, which may suppress breast cancer cell proliferation, while gma-miR4995, also from soybean, targets MALAT1 and NEAT1, two long non-coding RNAs involved in tumor progression, thereby exerting anti-tumor effects." (PMID 40565979, 2025). "It has been found that the up-regulation of lncRNA NEAT1 can increase the expression of Bcl-2 and EGFR, thus promoting the proliferation and invasion of tumor cells." (PMID 41186893, 2025). "Conversely, downregulated lncRNAs like NEAT1, MEG3, and PRINS normally function as tumor suppressor molecules that maintain epidermal homeostasis through pro-apoptotic and anti-inflammatory mechanisms." (PMID 40981386, 2025). "Among these, miR-124 is well known for its tumor suppressive role on CRC, as well as for its interaction with various oncogenic transcripts, including Nuclear Enriched Abundant Transcript 1 (NEAT1)." (PMID 39996790, 2025). "As the oncogenes of CRC, both nuclear enriched abundant transcript 1 (NEAT1) and Pseudouridine synthase 7 (PUS7) are involved in the initiation of the tumor through SIRT1/Wnt/β-catenin axis in the nude mice model." (PMID 40567502, 2025). "Long non - coding RNA - NEAT1 is likely to regulate the TLR4/NF - κB signaling pathway, thereby influencing the inflammatory response within the tumor microenvironment and facilitating the tumorigenic progression." (PMID 40110044, 2025). "Recent findings indicate that NEAT1 is upregulated in GC and that its overexpression can act as a scaffold to influence EZH2 expression, thereby affecting tumor invasion and metastasis." (PMID 41312360, 2025). "NEAT1, another lncRNA significantly overexpressed in TNBC, assumes a critical role in the regulation of tumor stemness." (PMID 39286016, 2024). "Both in vitro and in vivo experiments illustrated that NEAT1, delivered via EVs derived from M2 cells, stimulated the proliferation of OC cells, triggered apoptosis in CD8+ T cells, and facilitated tumor growth." (PMID 38903506, 2024). "Our findings indicate that A3B engages in selective RNA editing including targeting NEAT1 and MALAT1 long non-coding RNAs that are often highly expressed in tumour cells." (PMID 39322638, 2024). "Through direct interactions with known tumor suppressing miRNAs (MALAT1, HOTAIRM1), miRNA sponging (NEAT1, UCA1), and competition with miRNAs for mRNA binding (UCA1), lncRNAs drive oncogenesis in ATC via these dynamic interactions." (PMID 38785786, 2024). "Interestingly, in tumours predominantly expressing A3B, high NEAT1 or MALAT1 expression significantly correlated with reduced levels of the APOBEC-mediated mutation signatures, aligning with our hypothesis that NEAT1 and MALAT1 can regulate A3B activity by sequestration." (PMID 39322638, 2024). "LncRNA NEAT1 inhibits miR-155/Tim-3, induces CD8+ T cell apoptosis and limits anti-tumor activity against HCC." (PMID 37346034, 2023).
tumor (continued). "To further consolidate the pro-proliferative and pro-angiogenesis roles of NEAT1, we inoculated SKOV-3 cells and A2780 cells after gene expression manipulations into nude mice, and measured the in vivo tumor growth and blood vessels formation in tumor tissues." (PMID 37986114, 2023). "FOSB, JUNB, and JUN were highly activated in the NEAT1+MEL subcluster, and contained activator protein-1 (AP-1), which is widely involved in various tumor events including differentiation, proliferation, and apoptosis." (PMID 38065972, 2023). "The role of NEAT1 and KIF11 in cellular senescence and tumor growth in HCC was assessed both in vitro and in vivo." (PMID 37752791, 2023). "LncRNA NEAT1, which has been shown to play a carcinogenic role in various cancers, is also highly expressed in HCC and can promote tumor cell growth, metastasis and autophagy." (PMID 37837401, 2023). "Overexpressing NEAT1 competitively inhibits miR‐204‐5p and increases ATG3 expression, promoting autophagy to reduce sorafenib efficacy and induce tumor cell drug resistance." (PMID 37837401, 2023). "The nuclear paraspeckle assembly transcript 1 (NEAT1) has been showed to be involved in the regulation of cell cycle, proliferation and migration of tumor, apoptosis and ferroptosis." (PMID 37803093, 2023). "NEAT1 expression is closely related to the TNM stage, low survival rate and tumor recurrence in CRC thus, serving as an independent prognostic factor for tumor recurrence." (PMID 35814429, 2022). "In mouse models, the nuclear paraspeckle assembly transcript 1 inhibits the cGAS-STING signaling and cytotoxic T cell infiltration into the tumor microenvironment, thereby promoting tumor growth." (PMID 36359370, 2022). "As expected, many common tumor‐related lncRNAs, such as MALAT1, NEAT1, HULC, and PVT1, were identified in the H3K27ac chromatin immunoprecipitation sequencing (ChIP‐seq) data." (PMID 36307901, 2022). "A large number of studies have reported that targeted inhibition of DANCR, SLCO4A1-AS1, Linc00337, SNHG7/20, NEAT1, MALAT1, ES1 or MALAT1 can reduce the degree of malignancy of tumours at the cellular level and even in animal models." (PMID 35907897, 2022). "In clinical samples, lncRNA NEAT1 and MMP9 expressions were elevated in tumor tissues, while miR-132 expression was decreased." (PMID 35300348, 2022). "Several oncogenic lncRNAs, such as UCA1, NEAT1, TMPO-AS1 and OIP5-AS1, as well as some tumor suppressive lncRNAs, have been shown to participate in the chemoresistance of cancer cells." (PMID 36499136, 2022). "NEAT1 and VEGF-C were expressed at high levels in the tumour tissues compared to that in adjacent normal tissues, and miR-101 was significantly downregulated." (PMID 36434587, 2022). "Although the functional role of Lnc-NEAT1/miR-577 or miR-1224-5p/CCNT2 axis in LP has been identified, the regulatory role in tumor growth in vivo remains to be validated in further studies." (PMID 35012431, 2022). "Our results showed that miR-378a-3p acts as a tumor suppressor in CRC-SCs affecting the expression of two lncRNAs MALAT1 and NEAT1." (PMID 35814429, 2022). "Several ncRNAs, such as miR-491-3p, miR-613,and SUSD2 have been found to act as tumor suppressor genes in RB, but other ncRNAs, such as circ-E2F3, NEAT1, and TUG1 act as tumor promoter genes." (PMID 36619866, 2022). "The results showed that CAFs in P-LNs were associated with the high expression of NFIB, IGLC2, IGHG4, C7, and CCL19, while CAFs in tumor 3 had high expression of DIO2, LGALS1, WNT5A, NEAT1, and MMP11 in the tumor." (PMID 36569924, 2022). "Silencing ALKBH5 as a demethylated enzyme of m6A was reported to reduce the tumor behavior of CRC cells and inhibited the expression of proliferating cell nuclear antigen (PCNA) and the migration induced by NEAT1." (PMID 35676702, 2022). "The expression of HYMAI, NEAT1, XIST and FTX were negatively correlated with tumor diameter and significantly down-regulated during GIST progression." (PMID 34557343, 2021).
tumor (continued). "NEAT1 is upregulated in OC, positively correlated with FIGO stage, tumor grade, and distant metastasis." (PMID 34680193, 2021). "To verify NEAT1’s potential roles in GC angiogenesis, we firstly detected the secretion of VEGF, a key secretory protein in regulating tumor vascularization, in the culture medium (CM) of GC cells with different NEAT1 expression levels through ELISA assays." (PMID 34552925, 2021). "In addition, NEAT1 siRNA3 could effectively inhibit the level of NEAT1 in tumor tissues." (PMID 33982669, 2021). "ALKBH5 inhibits tumor motility and stemness by demethylating TIMP3, LncRNA NEAT1, WIF1, and LncRNA KCNK15-AS1." (PMID 33428593, 2021). "For instance, for MALAT1, NEAT1, and TUG1, both oncogenic and tumor suppressor effects have been reported." (PMID 34322395, 2021). "It has been shown that silencing Neat1 in mice prevents paraspeckle formation, which sensitizes preneoplastic cells to DDR activating cell death and impairing skin tumorigenesis." (PMID 34222014, 2021). "Accumulating evidence shows that aberrant expression of the long non-coding RNA (lncRNA) NEAT1 and microRNA-483 (miR-483) contribute to the epithelial-mesenchymal transition (EMT), invasion and metastasis of tumour cells." (PMID 33546665, 2021). "In this regard, NEAT1 has been shown to strengthen IL-6/STAT3 signaling and promote tumor growth and proliferation through nuclear trapping of mRNAs and proteins which acts as inhibitors of the IL-6/STAT3 signaling pathway." (PMID 34222014, 2021). "Some genes, such as MT2A, NEAT1, ATP1B1, and C11orf96, were highly expressed in tumour cells from ccRCC1." (PMID 34168986, 2021). "Our findings revealed that NEAT1 enhanced LSC differentiation through inactivating Wnt signaling, which plays a critical role in tumor initiation and progression." (PMID 34609794, 2021). "Further mechanistic analyses revealed that NEAT1 mediates PTX resistance via upregulating ZEB1 expression by sponging miR-194, a tumor suppressor miRNA." (PMID 32854207, 2020). "In this regard, the authors further found that BAP-1 (a chromatin modulator and potential tumor suppressor,) directly regulates NEAT1 expression and that BTC cells and patient samples show inverse BAP-1/NEAT1 expression patterns." (PMID 32331331, 2020). "Recent studies have shown that lncRNAs have important functions in modulating various tumor progression in HCC, such as growth arrest-specific 5 (GAS5), nuclear-enriched autosomal transcript 1(NEAT1), and taurine upregulated gene 1 (TUG1)." (PMID 32295144, 2020). "Further, we denoted invasion-associated lncRNAs which showed significant correlations with M1 and revealed their gradually increased expression levels along the tumor cell invasion trajectory, such as VIM-AS1, WWTR1-AS1, and NEAT1." (PMID 33505440, 2020). "On the other hand, lncRNA NEAT1 exerted its inhibitory effect on cGAS-STING pathway, mediating the immune escape of tumor cells to T cells." (PMID 32296457, 2020). "Downregulation of NEAT1 lncRNA inhibited the apoptosis of CD8+ T cells and enhanced their cytotoxic activity against tumor cells in vitro." (PMID 32083005, 2020). "The results indicates that inhibition of NEAT1 results in the increase in cGAS, STING level, and upregulation of phosphorylation of TBK1 and IRF3 in both of cell lines and tumor samples." (PMID 32296457, 2020). "On the other hand, NEAT1 and PTENP1, commonly known as tumor suppressors in various cancer types, have been shown to potentiate cell growth and tumor progression in breast cancer." (PMID 32392629, 2020). "We performed a series of experiments and analysis, including RT-qPCR, western blots, CCK-8 assay, and migration/invasion assay, to investigate the expressions of NEAT1, miR-23a-5p and KLF3, cell viabilities, and tumor growth in vivo." (PMID 31462890, 2019).